EGFR (epidermal growth factor receptor)
Diseases named in the same sentence as EGFR in open-access papers (continued):
Sharing a sentence is not in itself a finding about the gene and the disease.
lung adenocarcinoma (continued). "We evaluated the correlation between EGFR‐TKI resistance and lymphocyte infiltration, before and after acquiring EGFR‐TKI resistance, in 21 cases of lung adenocarcinoma, and further explored this by in vitro studies, using miRNA PCR arrays." (PMID 33305905, 2021). "Last, another independent study used two genetically engineered mouse models of lung adenocarcinomas corresponding to the two most common oncogene drivers in human lung adenocarcinoma, KRAS and EGFR." (PMID 34631560, 2021). "EGFR+, EGFR− and KRAS+ tumors were found to drive distinct radiographic phenotypes in a study with lung adenocarcinoma patients." (PMID 34164563, 2021). "Several driving mechanisms other than EGFR, such as ALK‐related fusion oncogenes, have been uncovered in lung adenocarcinoma and can also regulate ERK and AKT signaling." (PMID 33152171, 2021). "Epidermal growth factor receptor (EGFR) and anaplastic lymphoma kinase are two key oncogenes that trigger lung adenocarcinoma (LUAD)." (PMID 33981850, 2021). "In Sperduto’s research, significant prognostic factors included the classical four factors (age, KPS, extracranial metastases, and number of BM) and two molecular factors: EGFR and ALK mutant status, which frequently occurred in lung adenocarcinoma." (PMID 33194635, 2020). "Similar to our observations of KLF4 action in TNBC cells, KLF6 is a tumor suppressor that inhibits metastasis and the EGFR/AKT pathway in melanoma and lung adenocarcinoma." (PMID 32552913, 2020). "For instance, SKA3 binds EGFR and consequently activates PI3K–AKT, thus promoting lung adenocarcinoma metastasis." (PMID 33106477, 2020). "This evidence implies the important role of CD109 in EGFR-TKI therapies, and it also highlights translational relevance of CD109 as a diagnosis and therapeutic target in lung adenocarcinoma patients." (PMID 33375719, 2020). "In the context of acquired EGFR TKI resistance, phenotypic transformation encompasses epithelial to mesenchymal transition (EMT), transformation of adenocarcinoma of the lung (LUAD) to squamous cell carcinoma (SCC) or small cell lung cancer (SCLC)." (PMID 32292420, 2020). "Our studies have shown that the hub genes, such as VEGFA, EGFR, CASP3, and AKT1, as potential therapeutic targets of cinobufotalin injection correlated with the survival time of lung adenocarcinoma patients." (PMID 32148531, 2020). "FASN has been previously related to AKT/ERK/EGFR signaling pathways and the inhibition of the transcription factor STAT3 in lung adenocarcinomas." (PMID 32438613, 2020). "As expected, EGFR, ITGA2, KRAS, MMP9, NRAS and MAPK13 had higher levels in lung adenocarcinoma than in normal lung tissues." (PMID 32210363, 2020). "Resistin can also increase EGFR phosphorylation through the Toll-like receptor 4 (TLR4)/Src pathway and thereby promote lung adenocarcinoma metastasis." (PMID 33313320, 2020). "In the current cohort, there were 23.8% individuals still surviving to the last follow‐up, 57% cases with KPS ≥90, 42.8% patients at EGFR or ALK positive, and the vast majority of patients were lung adenocarcinoma." (PMID 33027555, 2020). "All patients were EGFR/KRAS wild-type, 14 cases of which were lung adenocarcinoma and 20 cases lung squamous cell carcinoma." (PMID 32775040, 2020). "We further assessed the role of ERβ5 in lung adenocarcinoma using PC9 cells, which harbor EGFR exon 19 deletions." (PMID 33585221, 2020). "Correlation analysis results showed that the expression of VEGFA, EGFR, CASP3, and AKT1 correlated with the median survival time of lung adenocarcinoma patients (P < 0.05)." (PMID 32148531, 2020).
lung adenocarcinoma (continued). "Targeted therapies, however, can be very effective against established BM from different entities, such as BRAF and MEK inhibitors in melanoma, EGFR and ALK inhibitors in lung adenocarcinoma, and immune checkpoint inhibitors in melanoma and lung cancer." (PMID 32918638, 2020). "Lung adenocarcinomas with ROS1 rearrangement were mainly solid in density (19 of 23, 83%), similar to EGFR-mutant (73%) or ALK-rearranged (88%) tumors, and tended to have a lobulated border (15 of 23, 65%)." (PMID 33005033, 2020). "This locus has neither been reported in the GWAS of UF or OC, however, GABBR2 is suggested to have an important role in EGFR signaling through the ERK1/2 pathway, as reported in lung adenocarcinoma." (PMID 31488892, 2020). "We report a case of EGFR wild-type and ALK-negative lung adenocarcinoma patient with multiple symptomatic BMs, who received apatinib together with brain radiation therapy." (PMID 32351894, 2020). "Thus, quantile 0.975 may not be used for prediction of EGFR mutation status of the bone metastases in patients with primary lung adenocarcinoma." (PMID 31174617, 2019). "The lung adenocarcinoma model LXFA 677 displayed high expression levels of EGFR and medium levels of p-EGFR as indicated by the median corrected normalized values (black arrow)." (PMID 31323891, 2019). "Recently we have reported that SFN stabilizes receptor tyrosine kinases such as EGFR and MET by facilitating their deubiquitination in lung adenocarcinoma cells." (PMID 30899432, 2019). "In this review we will briefly discuss EGFR, ALK, and K-Ras gene alterations in lung adenocarcinoma." (PMID 31134065, 2019). "Our experiments demonstrated that both EGFR and MEK1/2 inhibitors decrease EGF‐ and IFNγ‐induced PD‐L1 expression, potentially increasing immunogenicity of lung adenocarcinoma cells." (PMID 30972766, 2019). "A recent update to that research suggested that two additional factors, namely, EGFR and ALK alterations in patients with lung adenocarcinoma, can be used to better evaluate the prognosis of such patients." (PMID 31655564, 2019). "The overexpression of GAS5 varied inversely with the expression of EGFR pathway and IGF-1R proteins in lung adenocarcinoma tissues." (PMID 30853980, 2019). "Some studies showed that curcumin and its analogs can induce EGFR degradation in EGFR-TKI-resistant and -sensitive lung adenocarcinoma cells and sensitize the TKI-resistant NSCLC cells to gefitinib." (PMID 31196210, 2019). "Although HER2 amplification is a rare event in lung adenocarcinoma, it accounts for about 1–2% of total cases and up to 13% of NSCLC with acquired resistance to EGFR-TKIs." (PMID 31795465, 2019). "A total of 72 patients with lung adenocarcinoma (30 males and 42 females; age 55.9 ± 11.6 years old) who underwent DESCT scanning and EGFR and KRAS testing were included in this study." (PMID 31783917, 2019). "The most significantly focally amplified genes in lung adenocarcinomas are NKX2-1, MYC, TERT, MCL1 and MDM2, while in LSQCC the most amplified were SOX2, CCND1, FGFR1, MYC, YES1, MIR205 and EGFR." (PMID 30060526, 2018). "In cohort 1, the HS values of EGFR, KRAS, HER2, BRAF, and PIK3CA were calculated to estimate intratumor genetic heterogeneity in lung adenocarcinoma." (PMID 29518290, 2018). "As far as we know, this study is the first study to compare the efficacy of pemetrexed-based chemotherapy between HER2-mutant and groups of EGFR-mutant, ALK/ROS1-rearranged and KRAS-mutant lung adenocarcinoma." (PMID 29587667, 2018). "In addition, we found that lung adenocarcinoma with EGFR exon 19 mutation had more specific CT features (small lesion diameter, pleural retraction, and the absence of emphysema and fibrosis) as compared with EGFR wild type." (PMID 30235778, 2018).
lung adenocarcinoma (continued). "Our study indicates that, for lung adenocarcinoma patients with brain metastasis, a validated prognostic nomogram (KPS, smoking, EGFR-20 and Ca125) can more accurately predict the 1-year and 2-year survival of the patients before TKI therapy than other models." (PMID 29618796, 2018). "Four variables of the models (KPS, smoking, EGFR-20 and CA125) were all reported as factors for lung adenocarcinoma patients previously." (PMID 29618796, 2018). "We suggest that combined inhibition of EGFR and YAP can be a promising therapeutic strategy for EGFR mutant lung adenocarcinoma patients." (PMID 29321482, 2018). "In conclusions, for lung adenocarcinoma patients with brain metastasis, a validated prognostic nomogram (KPS, smoking, EGFR-20 and Ca125) can more accurately predict 1-year and 2-year survival of the patients." (PMID 29618796, 2018). "For lung adenocarcinoma patients with brain metastasis, a validated prognostic nomogram (KPS, smoking, EGFR-20 and Ca125) can more accurately predict the 1-year and 2-year survival of the patients before TKI therapy than other models." (PMID 29618796, 2018). "On this study we describe a landscape of genomic alterations in lung adenocarcinoma patients with WSE in the tumor suppressors SMARCB1 and ATM, in addition to the oncogenes EGFR, RET and KDR." (PMID 30093964, 2018). "In this work we focus on developing a gold nanoparticle contrast agent that targets the epidermal growth factor receptor (EGFR), which is expressed on the cell surface of most lung adenocarcinomas." (PMID 30408128, 2018). "Using lung adenocarcinoma cell lines, enhanced YAP1 expression and activity mediated by EGFR signaling was detected through enhanced protein stability." (PMID 29163769, 2017). "EGFR-TKI concentration and penetration of the blood-brain-barrier have remained a concern in treating lung adenocarcinoma patients with brain metastases." (PMID 29163842, 2017). "Using molecular and morphometric approach, 347 lung adenocarcinoma samples were analyzed for KRAS and EGFR sub-clonality, which was further correlated with clinical and pathological variables." (PMID 28501852, 2017). "Non-Asian patients with grade II–III or III lung adenocarcinoma have a less than 10% incidence of EGFR mutation and may also be appropriate for initiating systemic chemotherapy or immuno-chemotherapy promptly while awaiting the result of EGFR mutational analysis." (PMID 29232915, 2017). "By integrating two time-course microarray data in human lung adenocarcinoma cells, we specifically have identified some nested gene clusters and found that TGFB1, EGR1, EGR2, EGFR, IL6, JUN, and JUNB all are involved in these clusters." (PMID 28959347, 2017). "To explore the mechanisms of acquired EGFR TKI resistance in NSCLC, we established the gefitinib-resistant (GR) lung adenocarcinoma cells." (PMID 29190911, 2017). "The initial pathologic diagnosis was lung adenocarcinoma stage IIIa (pT3 pN1 Mx), KRAS wild-type, harboring EGFR exon 19 deletion and EML4-ALK rearrangement." (PMID 28938691, 2017). "Mutant EGFR genes have been reported to upregulate IL-6 and then activate the gp130/JAK/STAT3 pathway in primary human lung adenocarcinomas." (PMID 27362942, 2016). "The results indicated that high TLGWBR (≥259.85), EGFR wild-type, and high serum LDH were independent predictors of worse PFS and OS in all patients with advanced lung adenocarcinoma." (PMID 27336755, 2016). "They showed that miR-155, miR-25, and miR-495 were up-regulated only in the EGFR-wild-type/KRAS-wild-type, EGFR-mutant, and KRAS-mutant lung adenocarcinomas, respectively." (PMID 27005669, 2016). "In contrast, patients with EGFR-positive lung adenocarcinoma tended to present with GGO, and patients with KRAS-positive lung adenocarcinoma tended to present with a solid tumor that had limited tendency to metastasize to the lung and pleura." (PMID 27518729, 2016).
lung adenocarcinoma (continued). "On the other hand, studies with KrasLA1 mice, which develop lung adenocarcinoma through somatic activation of a KRAS allele carrying an activating mutation in codon 12 suggested that the presence of KRAS mutations was not sufficient to confer resistance to EGFR inhibition." (PMID 27458163, 2016). "Five common oncogenes, Kras, EGFR, ALK, ERBB2, and BRAF are represented in more than 50 % of lung adenocarcinomas." (PMID 26884725, 2016). "In fact, multifocal lung adenocarcinomas with AAH and BAC (lepidic) patterns develop at 3 to 5 weeks of age in transgenic mice expressing the del E748-A752 mutant version of mouse EGFR driven by the surfactant protein C promoter." (PMID 26422230, 2015). "Similar defects in EGFR signaling to Erk and Akt were observed in CIP4 KD lung adenocarcinoma cells, and these results implicate CIP4 in regulating EGFR levels and signaling." (PMID 25823823, 2015). "PC9 cells (Gef-sensitive EGFR mutant LAC cells) and A549 cells (Gef-resistant EGFR wild-type LAC cells) were exposed to Gefitinib (Gef, Iressa, the most commonly used TKI in lung adenocarcinoma) and/or Tamoxifen (TAM, the most commonly used SERM)." (PMID 25692143, 2015). "Analyses of five driver genes, including EGFR, KRAS, BRAF, HER2 and EML4-ALK, were performed in patients with treatment naïve lung adenocarcinoma." (PMID 25789627, 2015). "Current international guidelines recommend analysis of the following seven genes before starting palliative intent therapy for lung adenocarcinoma: KRAS, EGFR, ALK, ROS1, HER2, BRAF, RET." (PMID 26018876, 2015). "Nevertheless, a series of data suggest that the mutational load of lung adenocarcinoma in non-smoker patients (where the chance of detecting the EGFR mutation is the highest) is significantly lower, and that few (but critical) mutations may be enough to switch cells from normal to malignant." (PMID 25904052, 2015). "In an era of targeted therapy, the status of EGFR and ALK should be identified in patients with lung adenocarcinoma before treatment." (PMID 24992725, 2014). "According to our data, we detected similar expression levels of EGFR and ErbB2 in our HCC cells as compared to A549 lung adenocarcinoma cells, which belong to cells expressing low levels of these receptors." (PMID 24947784, 2014). "EGFR, KRAS and STK11 are all involved in the regulation of the mTOR signaling pathway, whose dysregulation has been reported to be important to lung adenocarcinoma." (PMID 25106096, 2014). "In summary, the microRNA, miR-133a, inhibits the expression levels of multiple oncogenic receptors, i.e., EGFR, IGF1R, and TGFBR1, and mediates cell growth and invasion in lung adenocarcinoma." (PMID 24816813, 2014). "Interestingly, we identified a group of miRNAs (including miR-19a, miR-19b, miR-195, miR-122 and miR-590-5p) that could be predictive of survival outcomes of non-smoking female lung adenocarcinoma patients who have EGFR mutations in Exons 18-21." (PMID 24282590, 2013). "Because EGFR-mutant tumours show lower 18F-FDG uptake in PET-CT scan, this case illustrates a rare presentation of EGFR-mutant lung adenocarcinoma with high 18F-FDG mutant lung adenocarcinoma." (PMID 22957291, 2012). "In addition to EGFR mutations and ALK rearrangements, genomic studies have also identified frequent copy number changes and somatic mutations affecting components of key signaling pathways in adenocarcinoma of the lung including KRAS, Her2, BRAF, C-MET, MEK1 and PIK3CA." (PMID 25562798, 2012). "In lung adenocarcinoma of hamsters, the overexpression of PKA, cAMP, CREB and phosphorylated CREB in β2-adrenergic receptor pathway and EGFR-specific phosphorylated tyrosine kinase, Raf-1 and ERK1/2 and their phosphorylated forms in EGFR pathway were observed." (PMID 21559252, 2011). "Support for a developmental sequence from AAH to adenocarcinoma also comes from conditional oncogenic mouse models for lung adenocarcinoma, in which KRAS or EGFR genes are activated." (PMID 21731750, 2011).
lung adenocarcinoma (continued). "We have demonstrated that predictive models of EGFR TKI sensitivity can classify both out-of-sample cell lines and lung adenocarcinomas." (PMID 17096850, 2006). "Similarly, LSD1 inhibitors can resensitize CRPC to AR blockade, but in lung adenocarcinoma, LSD1 inhibition disrupts EGFR and KRAS pathways with variable effects on tumor growth." (PMID 41601922, 2026). "Collectively, our findings suggest that pathologic downregulation of TSPX in NSCLC, especially in lung adenocarcinoma, results in upregulation of AREG, EREG, FOSL1, MYC, and PLAU, thereby potentiating the EGFR signaling pathway and leading to the initiation and/or exacerbation of cancer development." (PMID 39858622, 2025). "Despite epidermal growth factor receptor (EGFR) is a pivotal oncogene for several cancers, including lung adenocarcinoma (LUAD), how it senses extracellular matrix (ECM) rigidity remain elusive in the context of the increasing role of tissue rigidity on various hallmarks of cancer development." (PMID 40165020, 2025). "The remaining half of the HNF4α-positive non-mucinous adenocarcinomas were totally TTF-1-negative (8/8, 100%) and never harbored EGFR mutations (0/8, 0%), suggesting that they were the non-TRU-type lung adenocarcinomas." (PMID 38710944, 2025). "TKIs significantly increase the responsiveness of lung adenocarcinomas with mutant EGFR, but they do not seem to improve survival for unselected individuals." (PMID 40728967, 2025). "Dynamic glyco-signature surfing: Differential sialoglycan patterns can distinguish TNBC sub-clones (BRCA-mutant vs. non-mutant) and have been exploited to circumvent wild-type EGFR down-regulation in EGFR-T790M lung adenocarcinoma." (PMID 41155938, 2025). "In this study, we confirm the frequencies of somatic mutations in these genes in the Mexican population, with 24% for EGFR and 16% for KRAS, compared to 20% and 10%, respectively in the Carrot-Zhang recent study that included Mexican patients with lung adenocarcinoma." (PMID 40430005, 2025). "Serum carcinoembryonic antigen (CEA) has potential prognostic and monitoring significance in lung adenocarcinoma (LUAD) patients undergoing different treatments, such as epidermal growth factor receptor (EGFR)‐tyrosine kinase inhibitors (TKIs) and chemotherapy." (PMID 40856433, 2025). "Interestingly, Rab25 downregulation was found to impair EGFR signalling, with a consequent reduction in ERK and AKT phosphorylation in radioresistant lung adenocarcinoma and nasopharyngeal carcinoma cells." (PMID 40164572, 2025). "Compared to EGFR gene mutations, ALK rearrangement is more likely to occur in younger, non-smoking or light-smoking lung adenocarcinoma patients." (PMID 41378298, 2025). "When performing driver mutation testing in patients with lung adenocarcinoma, it is preferable to use next‐generation sequencing (NGS), which can detect a broad spectrum of mutations, including EGFR L861R, rather than a single‐plex EGFR assay." (PMID 41350121, 2025). "In this patient, lung adenocarcinoma remained progression-free for two years and five months with CBDCA-PEM plus ravulizumab, well beyond the approximately 5.5 month median PFS reported for this regimen in EGFR-TKI-resistant NSCLC." (PMID 40827190, 2025). "In lung adenocarcinoma, sustained NICD signaling has been shown to promote the EMT pathway, cancer stemness, metabolic reprogramming, and therapeutic resistance, with a combined effect of the KRAS and EGFR pathways." (PMID 41451346, 2025). "Additionally, after treatment with different concentrations of EGFR-TKIs for different durations, MCAM expression gradually increased, suggesting its potential involvement in lung adenocarcinoma resistance to EGFR-TKIs." (PMID 40713600, 2025). "In contrast, monotherapy with ICIs has not significantly improved efficacy in EGFR-mutant lung adenocarcinoma patients." (PMID 41357203, 2025).